SCARNA16 (small Cajal body-specific RNA 16)
Synonyms: ACA47
Gene: Small Cajal body-specific RNA gene on chromosome 17 (77,089,307 to 77,089,493, forward strand). Ensembl gene ENSG00000275143.
Gene Ontology:
Biological process: RNA processing
Cellular component: nucleolus
Homologues: Orthologues: chimpanzee SCARNA16 (99% identical), macaque SCARNA16 (94% identical), guinea pig SCARNA16 (90% identical), dog SCARNA16 (86% identical), rabbit SCARNA16 (71% identical).
Diseases named in the same sentence as SCARNA16 in open-access papers:
SCARNA16 is named in the same sentence as 2 diseases in open-access papers, as found by Europe PMC text mining. Sharing a sentence is not in itself a finding about the gene and the disease.
SCARNA16 shares sentences with these, for which no sentence is quoted: gastric cancer (1 paper); tumor (1).